BDNF (brain derived neurotrophic factor)
Diseases named in the same sentence as BDNF in open-access papers (continued):
Sharing a sentence is not in itself a finding about the gene and the disease.
Cognitive impairment (continued). "Our failure to observe an association between BDNF levels and cognition in the smoking group with the Met/Met genotype could be due to lack of enough BDNF to counteract the smoking-induced cognitive impairment." (PMID 30659208, 2019). "However, it is noteworthy that in our present study, smokers had some cognitive deficits, but not lower BDNF levels." (PMID 30659208, 2019). "Thus, knockout of BDNF or TrkB in the hippocampus results in JAK2/STAT3, C/EBPβ, and δ-secretase upregulation and activation, resulting in increased neuroinflammation and neuronal cell death, leading to cognitive impairments." (PMID 31315045, 2019). "Furthermore, another group reported that moderate treadmill exercises could ameliorate Aβ deposition and cognitive impairment, possibly due to the PGC-1α/FNDC5/BDNF pathway." (PMID 30355327, 2018). "In addition, BDNF is not correlated with the severity of the positive and negative symptom and cognitive impairment." (PMID 29896133, 2018). "Low BDNF may contribute to the pathogenesis of schizophrenia indeed, however, it may not contribute to its cognitive impairments directly." (PMID 29896133, 2018). "By increasing BDNF (brain-derived neurotrophic factor) serum concentration and inducing NOS-3 (nitric oxide synthase-3) activity resveratrol may have possible therapeutical effects on cognitive impairments and dementias especially in those characterized by defective cerebrovascular blood flow." (PMID 30469326, 2018). "Our findings suggest that BDNF may not be involved in the pathophysiology of heroin dependence, but more studies about cognitive impairment in heroin addiction are needed." (PMID 28403087, 2017). "Considering that several previous studies have shown the regulation of CREB and BDNF neurotrophic signaling by MA stimulation of the points GV20 and HT7, the limited upregulation of Creb and Bdnf gene expressions shown by MA after cognitive impairment in this study was unexpected." (PMID 28408940, 2017). "Interestingly, this effect is not observed in ovariectomized heterozygous BDNF Val66Met females, suggesting that circulating ovarian hormones induce cognitive impairment in Met carriers." (PMID 28993643, 2017). "Thus, in this study, we used the CUMS model to investigate the antidepressant-like activity and cognitive impairment effects of SCE, moreover, the BDNF/TrkB/ERK/CREB and PI3K/AKT/GSK-3β signaling pathways were determined to illustrate the action mechanism of SCE." (PMID 28761074, 2017). "7,8-Dihydroxyflavone (7,8-DHF), a tyrosine kinase B agonist that mimics the neuroprotective properties of brain-derived neurotrophic factor, which can not efficiently deliver into the brain, has been reported to be useful in ameliorating cognitive impairment in many diseases." (PMID 27965573, 2016). "The role of BDNF and TrkB in the pathophysiology and cognitive deficits of AD has been well reported in previous studies and it seems that the protective role of CAF against memory impairment in AD might be resulted from the activation of BDNF/TrkB signaling." (PMID 27110749, 2016). "However, even short-term feeding of the HFS diet results in cognitive impairment and potentiates the negative impact of mild brain injury on BDNF levels, synaptic plasticity and cognitive functioning." (PMID 26349802, 2015). "In conclusion, our findings support the hypothesis that BDNF alterations are involved in neurodegenerative mechanisms and suggest that low BDNF levels are nonspecific markers of neurodegeneration common to several cognitive disorders." (PMID 24024214, 2013).
Cognitive impairment (continued). "As for BDNF, the microtubule-dependent retrograde trafficking of NGF appears to be defective, both in models of age-dependent cholinergic degradation (the aged Fischer 344 rat model, which shows cognitive impairment) and transgenic models of Down’s syndrome and AD." (PMID 22654714, 2011). "According to these findings, we hypothesize that the BDNF produced by hUC-MSCs may enhance the survival of neural stem/progenitor cells in the subgranular zone of the dentate gyrus and improve astrocytes in the APP/PS1 hippocampus, thereby indirectly mitigating inflammation and cognitive deficits." (PMID 40564462, 2025). "Supportive of this hypothesis are several studies, which found that exergaming increased BDNF levels in chronic stroke, older adults and Parkinson’s disease patients, as well as IGF-1 and other neuroplasticity-indicative biomarkers in people with mild cognitive impairment." (PMID 40182756, 2025). "For instance, HPC protocols could mitigate cognitive deficits in high-altitude travelers or military personnel Additionally, in clinical contexts such as stroke or cardiac arrest, HPC may complement existing therapies by preserving cholinergic integrity and enhancing BDNF signaling." (PMID 40354376, 2025). "Similarly, it has been demonstrated that oroxylin A reduces cognitive impairment brought on by the permanent blockage of bilateral common carotid arteries (2VO) by suppressing activated microglia and upregulating the expression of CREB and brain-derived neurotrophic factor (BDNF)." (PMID 40243521, 2025). "For instance, the expression level of BDNF, defined as a hub gene in this study, is decreased in Alzheimer's disease by lowering the phosphorylated cyclic adenosine monophosphate (cAMP) response element binding (CREB) protein, which may lead to synaptic dysfunction and cognitive impairments." (PMID 36518809, 2022). "The expression levels of TrkB, BDNF, and SYP were upregulated within the hippocampal DG of Mn-exposed mice after NSC transplantation, suggesting that NSC-induced expression of these proteins may play a critical role in rescuing the cognitive deficits induced by Mn exposure." (PMID 33815871, 2021). "Because exercise-induced BDNF and CB1R activations are dependent on exercise intensity and both effectors are involved in exercise-induced hippocampal neurogenesis, this synergism of BDNF and CB1R responding to exercise may provide more beneficial effects on improving cognitive deficits." (PMID 32485872, 2020). "If so, and considering the fact that in our study similar circulating levels of BDNF were seen in both experimental groups but cognitive performance was suppressed in hypoxia, one could conclude that acute elevation of BDNF did not compensate for hypoxia-induced cognition impairment." (PMID 32759658, 2020). "In addition, acute elevation of BDNF did not compensate for hypoxia-induced cognition impairment." (PMID 33096634, 2020). "To determine whether SCO treatment diminished the levels of BDNF or phosphorylated CREB (pCREB) and to determine whether this contributed to the neuroprotective effects of FSJ on SCO-induced hippocampal neurogenesis and cognitive impairment, we examined BDNF and pCREB levels in the hippocampus." (PMID 26939918, 2016). "Serum levels of BDNF, BACE1, VEGF, GFAP, and IL-1β were evaluated through ELISA in patients with and without cognitive impairments." (PMID 40291844, 2025). "Aβ oligomers significantly reduce BDNF expression, partly due to CREB dysfunction, while the restoration of CREB/BDNF signaling improves cognitive deficits, regardless of Aβ pathology, in various models." (PMID 41007261, 2025). "Our study is the first meta-analysis to evaluate the levels of serum BDNF in T2DM patients and HCs and compare the levels between T2DM patients with or without cognitive impairment." (PMID 38648255, 2024).
Cognitive impairment (continued). "We compared the BDNF level between T2DM and HC groups (P < 0.001, I2 = 99%), and between the T2DM with or without cognitive impairment groups (P < 0.001, I2 = 90%) using a random-effect model since the heterogeneity test showed the I2 value >50%." (PMID 38648255, 2024). "Our study’s mediation analysis suggests that although BDNF is a biomarker influenced by T2DM and cognition, it does not mediate the relationship between cognitive impairment and diabetes." (PMID 36936159, 2023). "Therapeutic agents directed at mitigating tau aggregation and clearing Aβ1-42, and delivery of growth factor genes (BDNF, FGF2), have ameliorated cognitive deficits, but these approaches did not prevent or stop AD progression." (PMID 37369719, 2023). "There were significantly higher plasma concentrations of NfL (p = 0.032) and lower levels of BDNF (p = 0.002) in SUD patients with moderate–severe cognitive impairment than in those without cognitive impairment." (PMID 36674698, 2023). "Increased NfL/BDNF ratio were observed in both SUD patients with and without cognitive impairment, but in those with moderate/severe cognitive impairment, this index was notably higher." (PMID 36674698, 2023). "BDNF alterations were observed in both SUD patients with and without cognitive impairment, but especially in those with moderate/severe cognitive dysfunction." (PMID 36674698, 2023). "The results of the mediation analysis suggest that although BDNF is a biomarker affected by T2DM and cognition, it does not play a mediator role between cognitive impairment and diabetes." (PMID 36936159, 2023). "Although it has been consistently shown that ELS decreases hippocampal BDNF expression levels and impairs cognition, to our knowledge, the role of the BDNF-TrkB pathway in ELS-induced cognitive deficits has not been empirically tested." (PMID 37225683, 2023). "Binary logistic regression analysis was then used to assess the potential for the NfL/BDNF ratio alone to be a good predictor for discriminating between SUD patients with and without cognitive impairment (assessed by MoCA)." (PMID 36674698, 2023). "Yet so far, the relationship between peripheral BDNF levels and cognition in patients with LLS has not been explored, either which specific domains of cognitive deficits would be correlated with altered BDNF levels if any." (PMID 34239458, 2021). "One meta-analysis found that in AD, but not mild cognitive impairment (MCI)—which is conceptualized as a transitional stage between normal cognition and dementia—BDNF levels are significantly lower, suggesting that peripheral changes are more easily detected at later stages in the disease." (PMID 36970903, 2023). "However, the extent to which circulating BDNF correlates with human brainactivity during learning has not been demonstrated and the extent to which lower circulatingBDNF may be indicative of the neural correlates of cognitive impairment in schizophrenia hasnot been shown." (PMID 25162472, 2015). "Thus, we have found that monitoring BDNF could help to identify AUD patients with and without cognitive impairment with high accuracy." (PMID 36674698, 2023). "pCREB, BDNF, and PSD-95 decreased in the hippocampus, while CREB did not change; so, 666-15 contributed to the transmission of pain signals, suppressed the activation of the CREB/BDNF signaling pathway in the hippocampus, and weakened the treatment effect of resveratrol on cognitive disorders." (PMID 36478990, 2022).
Anxiety (1,042 papers, 2007 to 2026). Intense feelings of nervousness, tension, or panic often arise in response to interpersonal stresses. "This study investigated the role of astrocytic BDNF in modulating susceptibility to stress-induced anxiety." (PMID 40777598, 2025). "Activation of BDNF and its receptor tyrosine kinase receptor B (TrkB) can mitigate stress-induced impairments in fear memory extinction, thereby ameliorating anxiety-like behaviors associated with PTSD." (PMID 40453656, 2025). "In regards to anxiety symptomatology, assessed through higher Beck anxiety scores, we observed an 86.6% posterior probability that higher anxiety was linked to lower plasmatic BDNF levels (β = -0.5, CI95%[-1.41, 0.35], pd = 86.6%, ps = 81.6%)." (PMID 41164095, 2025). "•Deep phenotyping showed increased levels of the cytokine CCL2 and brain-derived neurotrophic factor, reduced apolipoprotein A1 and ipsilateral dorsal root ganglion atrophy, and with increased anxiety were associated with CPIP." (PMID 39909798, 2025). "Based on our exploratory study, we provide clinicians with additional diagnostic tools for CPIP, including DRG MRI, ApoA1, and BDNF serum levels, and anxiety screening with the STAI test." (PMID 39909798, 2025). "Alterations in BDNF signaling pathways have been associated with anxiety-like behaviors and the development of anxiety disorders." (PMID 40777598, 2025). "Our results further support the critical role of BDNF in modulating susceptibility to stress-induced anxiety." (PMID 40777598, 2025). "These behavioral alterations are associated with dysregulation of the CaMKIV/CREB/BDNF signaling pathway in key brain regions involved in anxiety regulation, including the prefrontal cortex, amygdala, hippocampus, and hypothalamus." (PMID 41301404, 2025). "Future research should address these limitations to improve our understanding of the brain-derived neurotrophic factor, personality and anxiety association with nicotine use in women." (PMID 40806241, 2025). "Deep phenotyping based on the pathophysiology of nerve damage and persistent low-grade inflammation identified ipsilateral DRG atrophy, in combination with low ApoA1, elevated BDNF, and high anxiety levels, as the best additional diagnostic tools." (PMID 39909798, 2025). "BDNF is known to modulate synaptic plasticity, particularly in brain regions implicated in anxiety and fear, such as the amygdala and the hippocampus." (PMID 38376041, 2024). "In conclusion, the difference in pre-and postoperative BDNF levels suggests that it is associated with anxiety." (PMID 38907644, 2024). "This stress-induced anxiety is associated with persistent upregulation of BDNF in the basolateral amygdala." (PMID 39275174, 2024). "In conclusion, this study demonstrated higher levels of BDNF in saliva in students who had depressive symptoms, whereas this association is lacking with other common psychological symptoms in this population (anxiety, stress, and insomnia)." (PMID 38396487, 2024). "Disrupted synaptic plasticity, particularly in the hippocampus, underlies susceptibility to social defeat stress and ethanol withdrawal-induced anxiety, associated with changes in BDNF, PSD-95, and NR2B levels." (PMID 39275174, 2024). "For example, a study reported that the anxiety trait was associated with BDNF polymorphism in patients with panic disorder." (PMID 39408702, 2024). "Acting in the amygdala, BDNF provides a mechanistic link between alterations in metabolic function associated with anxiety." (PMID 38672441, 2024). "This impairment was associated with reduced BDNF levels in the hippocampus and correlated with anxiety-like behavior displayed by the animals." (PMID 38645426, 2024). "The previous study revealed that the decline in the level of BDNF caused anxiety-like behavior through the zebrafish model." (PMID 39012662, 2024).
Anxiety (continued). "Our study indicates that anxiety (trait and state) and neuroticism are interacting with the BDNF gene rs6265 polymorphism in alcohol-dependent women." (PMID 38928154, 2024). "Our study shows that the BDNF Met allele influenced self-reported anxiety when the presence of APOE e4 and the interaction with APOE e4 was considered." (PMID 38279143, 2024). "On the basis of these data, the BDNF Met allele is associated with an increase in anxiety-like behavior in females that emerges during the period of sexual maturity." (PMID 38732283, 2024). "Contrary to the negative findings when examined separately, there seems to be an association between the BDNF Met risk allele and self-reported anxiety when controlling for the APOE e4 + and APOE*BDNF interactive effects." (PMID 38279143, 2024). "In the rat model of T2D induced by HFD and a low dose of STZ, anxiety-like behavior was associated with oxidative stress and low levels of BDNF in the amygdala." (PMID 38279738, 2024). "In the present study, we examined the effects of PS, ELF‐EMF, and simultaneously PS and ELF‐EMF on anxiety‐like behaviors, and expression of synaptic plasticity associated proteins (BDNF and GAP‐43) and neural cell apoptotic factor, cas‐3." (PMID 36942730, 2023). "The results indicate an important role of BDNF in mechanisms underlying anxiety and repetitive behavior in ASDs and implicates BDNF–DA crosstalk in the autistic-like phenotype of BTBR mice." (PMID 37239153, 2023). "Other studies have also found an association between lower serum BDNF levels and higher levels of anxiety and depressive symptoms in individuals with IBS." (PMID 37745409, 2023). "Our results show that this TrkB isoform participates in the control of aggression, anxiety, and depressive-like behavior and in the regulation of BDNF system functioning in ASC mice (genetically predisposed to depressive-like behavior)." (PMID 37761014, 2023). "At the level of the periaqueductal grey matter, the BDNF-TRKB system is involved in the pathophysiologic mechanisms underlying several anxiety and depressive disorders and is the target of several antidepressant drugs." (PMID 37189737, 2023). "Loss of NGFR, which is a low-affinity receptor for BDNF and primarily expressed in basal forebrain cholinergic neurons, increases anxiety-like behavior in mice." (PMID 36834565, 2023). "Further research is needed to clarify the mechanisms underlying the relationship between BDNF and anxiety and to identify the specific promoters involved." (PMID 37189402, 2023). "The Val66Met mutant of the BDNF gene reduces proBDNF carriers to the less frequent Met allele, which has been associated with a reduced capacity for managing stressful situations, anxiety, or impaired memory function." (PMID 36769269, 2023). "The rs7124442 and rs2049046 BDNF polymorphisms are associated with a higher body mass index and anxiety symptoms in FM individuals." (PMID 37189737, 2023). "Nevertheless, previous experiments with hippocampal BDNF overexpression suggest that BDNF does play an important role in the mechanisms underlying anxiety and repetitive stereotypical behavior; these mechanisms are known to be disturbed in ASDs." (PMID 37239153, 2023). "In CP deficient mice, increased anxiety is associated with elevated levels of plasma corticosterone and decreased levels of serotonin and NA, as well as brain-derived neurotrophic factor (BDNF) and its receptor." (PMID 38001850, 2023). "BDNF overexpression in the dentate gyrus also reverses the anxiety and autism-like phenotypes caused by neonatal isolation." (PMID 36979479, 2023). "Neurotrophic factors such as brain-derived neurotrophic factor (BDNF) are also implicated in anxiety." (PMID 35998298, 2023). "This study aimed to explore the relationship among BDNF Val66Met polymorphism, plasma BDNF level and anxiety-related trait in Chinese PD patients." (PMID 35815047, 2022).